ACACA (acetyl-CoA carboxylase alpha)
Diseases named in the same sentence as ACACA in open-access papers (continued):
Sharing a sentence is not in itself a finding about the gene and the disease.
Obesity (20 papers, 2011 to 2025). Accumulation of substantial excess body fat. "Obesity in humans is associated with elevated ACACA expression and IL-17 production from memory CD45RO+ CD4 T cells." (PMID 39763655, 2024). "Acetyl-CoA carboxylase alpha (ACACa) is the rate-limiting enzyme in fatty acid synthesis and is believed to be a novel target for endocrine disease, e.g., diabetes and obesity." (PMID 32724489, 2020). "An increase in total energy expenditure and a reduction in body fat mass as well as skeletal muscle triglyceride levels have been observed in ACACA knockout mice, thus highlighting the role of ACACA in diet-induced obesity." (PMID 31011474, 2019). "The multiple alterations on cytoplasmic acetyl-coA-forming enzymes complemented with increased activity of rate-limiting ACACA, suggest possible dysregulation of fatty acid biosynthesis pathway in adipocytes during obesity." (PMID 27180971, 2016). "A large number of nanomolar small-molecule ACACA inhibitors have been developed, and several have been evaluated in clinical trials for metabolic diseases such as obesity and metabolic syndrome." (PMID 25246709, 2014). "Interestingly, we observed a significant positive correlation between ATF4 and SREBP1, FASN, and ACACA expression in PBMCs from children with obesity." (PMID 40806129, 2025). "We selected five of these (ACACA, CETP, CTGF, S100A8, S100A9) for further analyses based on reported adipose or adipocyte gene expression changes in response to weight loss/dietary intervention (ACACA, CETP, CTGF), and/or associations with obesity or related traits (GWAS, and/or other literature)." (PMID 25651499, 2015). "Long non-coding RNAs, particularly MEG3, are involved in obesity through regulation of lipogenic genes including ATF4, FTO, SREBP1, FASN, and ACACA." (PMID 40806129, 2025). "The mRNA expression of SREBP1 (p = 0.0176), FASN (p = 0.0412), ACACA (p = 0.0255), FTO (p < 0.0001), and ATF4 (p < 0.0001) was significantly reduced in the obesity group compared to the control group." (PMID 40806129, 2025). "Our analysis showed significant negative correlations between added sugar intake and the expression of SREBP1, ACACA, and FTO in PBMCs from children with obesity." (PMID 40806129, 2025). "Presently, due to the vital function of ACACA in controlling the synthesis of fatty acids, it has become a critical research target for metabolic diseases such as NAFLD, obesity, and diabetes." (PMID 38395901, 2024). "ChREBP activation in WAT is altered in obesity, resulting in the downregulation of ChREBPβ, ACLY, ACACA, FASN, and ELOVL6." (PMID 32085416, 2020). "ACACA expression was also lower in boys with obesity than in boys without obesity (p = 0.001), girls with obesity (p = 0.011), and girls without obesity (p = 0.003)." (PMID 40806129, 2025). "MEG3 and FTO showed sex-dependent expression in children without obesity, while additional sex-related differences were observed for SREBP1, FASN, ACACA, FTO, and MEG3 in children with obesity." (PMID 40806129, 2025).
Hepatic steatosis (19 papers, 2011 to 2025). Steatosis is a term used to denote lipid accumulation within hepatocytes. "Preclinical models demonstrated that PE-CSLT modulates AMPK/SREBP1/ACACA/PPARa signaling to attenuate hepatic steatosis and dyslipidemia, providing mechanistic support for its therapeutic potential." (PMID 40708046, 2025). "The expression analysis of hepatic steatosis-related genes showed that gallic acid treatment inhibits the expression of the ACACA and FASN genes in the liver." (PMID 34204038, 2021). "It is noteworthy that, protein abundance of acetyl-CoA carboxylase alpha (ACCα) being greater increase compared with the control group, hepatic steatosis (fatty liver group) led to lower p-ACCα and p-ACCα/ACCα." (PMID 32230804, 2020). "It has been suggested that inhibition of ACACA may be useful in treating a variety of metabolic disorders, including metabolic syndrome, type 2 diabetes mellitus, and fatty liver disease." (PMID 28827398, 2017). "Expression of hepatic genes involved in cholesterol metabolism (SREBP2, HMGCR, and ApoB) and lipogenesis (SREPB1c, SCD-1, FAS, and Acacα) was suppressed in the experimental group, and may have favorably affected hyperlipidemia and hepatic steatosis induced by the high-fat diet." (PMID 22027268, 2011). "Our findings identified SNPs significantly associated with disease risk, demonstrated altered expression of immune (IL-6, IL-8), antioxidant (SOD3, HMOX1), and lipogenic (ACACA, FASN) genes, and confirmed hepatic steatosis via ultrasonography." (PMID 41012815, 2025). "Recent studies have shown that inhibiting SREBP1, ACLY, ACSS2, ACACA, and FASN can improve fatty liver disease." (PMID 37065701, 2023). "Earlier studies document that upregulated lipogenic gene expression, such as for fatty acid synthase (FASN) and acetyl-CoA carboxylase (ACACA), was resulting in increased SREBP-1c expression, which leads to hepatic steatosis." (PMID 33261004, 2020). "The transcripts of ACACA, FASN, SCD, FADS2 and FABP1 in chickens with fatty liver were significantly increased compared with those in chickens without fatty liver." (PMID 29642504, 2018). "It was also found that activated AMPK suppresses the expression of ACACA and FASN, which may reduce fatty acid synthesis, serum triglycerides, and cholesterol levels, thereby alleviating hepatic steatosis." (PMID 40176148, 2025).
steatosis (14 papers, 2013 to 2025). Increased lipid within the cytoplasm of cells. "Several studies have shown that ACACA is highly expressed in a model of steatosis which is consistent with our results." (PMID 38395901, 2024). "While we have established APOA1 as a key functional regulator in OA-induced steatosis, the precise transcriptional regulatory relationship between APOA1 and downstream genes such as ACACA, FASN, CPT1, and APOB remains to be fully elucidated." (PMID 41463887, 2025). "However, in contrast to the hepatocyte steatosis model (MOD) group, the QUE group displayed a significant reduction in ACACA mRNA expression (p < 0.01), while the other three drug groups remained unchanged (p > 0.05)." (PMID 40708046, 2025). "Notably, downstream of ACACA, the gene expression of Fatty Acid Synthase (FASN) corroborated this observation, demonstrating a significant reduction in lipogenesis in our steatosis model, and a significant elevation in lipogenesis under both nSMase and aSMase inhibition." (PMID 38474427, 2024). "In our experiments, LPS alone did not affect the levels of ACACA, ACACB nor FASN in HepG2 cells, indicating that it does not induce DNL-mediated steatosis in HCC cell model either." (PMID 32284043, 2020).
hepatocellular carcinoma (11 papers, 2022 to 2025). A malignant tumor that arises from hepatocytes. "In hepatocellular carcinoma, ACACA has been identified as a central gene associated with poor prognosis." (PMID 40823088, 2025). "USP22 deubiquitinates and enhances the stability of PPARγ protein, thereby promoting the synthesis of FASN, ACLY, and ACACA, and facilitating the malignant progression of hepatocellular carcinoma." (PMID 39944823, 2025). "In hepatocellular carcinoma, cells exhibit abnormally active lipid synthesis capacity, and the expression of ACACA is positively correlated with tumor malignancy." (PMID 41169354, 2025). "It is reported that in the prognosis model of hepatocellular carcinoma, the genes (NFS1, CISD1, ACSL3, NQO1, SLC7A11, GPX4) that can protect hepatocytes with ferroptosis and the genes (ACACA, CARS, G6PD, SLC1A5) that induce ferroptosis are all up-regulated in HCC, and are related to poor prognosis." (PMID 36387286, 2022).
metabolic syndrome (11 papers, 2014 to 2025). A cluster of metabolic risk factors for CARDIOVASCULAR DISEASES and TYPE 2 DIABETES MELLITUS. "Prior studies have reported that pharmacologic inhibition of ACACA decreased the mortality of patients with metabolic syndrome via limiting fatty acid synthesis in lipogenic tissues." (PMID 38049827, 2023). "Yet, the functions of ANGPTL4 and ACACA in dyslipidemia of obstructive sleep apnea (OSA) remain unclear." (PMID 38574398, 2024). "ACACA was traditionally recognized as target of metabolic syndrome." (PMID 31920968, 2019).
diabetes (9 papers, 2017 to 2024). "SREBP is involved in the regulation of various lipogenic genes such as ACACA, FASN, ACSL1 and MCAT which are found to be overexpressed in diabetes." (PMID 31569751, 2019).
Insulin resistance (9 papers, 2014 to 2025). Increased resistance towards insulin, that is, diminished effectiveness of insulin in reducing blood glucose levels. "ACACA showed inverse correlations with anthropometric and insulin resistance markers and a positive correlation with HDL-C." (PMID 40806129, 2025). "In insulin-resistant (IR) children, MEG3, ATF4, FTO, ACACA, and SREBP1 were reduced, while FASN was increased." (PMID 40806129, 2025). "Only expression of ACACA and FASN are significantly decreased in obese subjects with insulin resistance." (PMID 37047391, 2023).
liver cancer (8 papers, 2022 to 2025). An epithelial or non-epithelial malignant neoplasm that arises from the liver. "Decreased expression of ACACA or ACACB is associated with liver cancer suppression, as demonstrated in rats." (PMID 35159548, 2022). "Particularly, the expression of ACACA was significantly up-regulated in induced liver cancer stem cells (M3CSs and G2CSs) compared to their parent cells." (PMID 38584256, 2024). "In HepG2 liver cancer cell, acetate activated ACACA and FASN expression and increased de novo lipid synthesis under hypoxia, thus promoting cell survival." (PMID 35057851, 2022). "IN HPA database, immunohistochemistry showed that the expressions of APEX1, ME1, S100A10 and ACACA in liver cancer tissues were significantly higher than those in paired normal liver tissues, while ADH1C, and CYP2C9 were expressed at low levels in tumor tissues compared with adjacent normal tissues." (PMID 36456877, 2022). "To verify the important role of ACACA in HCC, we used the HCC patient samples and SD rat orthotopic liver cancer models." (PMID 38584256, 2024). "Additionally, we confirmed that the expression of ACACA in HCC patient, SD rat liver cancer model and cell lines presented an obviously higher expression than that in normal tissues and cell lines." (PMID 38584256, 2024).
lung cancer (8 papers, 2016 to 2025). A malignant neoplasm involving the lung. "Also, our study found that ACACA mRNA expression is significantly higher in lung cancer patients with EGFR mutations than those with wild-type EGFR." (PMID 41169354, 2025). "Our findings demonstrated that lung cancer patients with elevated ACACA mRNA expression had a worse prognosis." (PMID 41169354, 2025). "In our study, we also found that ACACA expression is related to mutations of common driver genes in NSCLC, which agrees with recent research that common driver gene mutations in lung cancer, such as KRAS, EGFR, ROS1 and ALK, are closely related to metabolism." (PMID 41169354, 2025). "Furthermore, in vitro studies demonstrated that ACACA inhibition suppresses fatty acid synthesis and tumor growth in lung cancer and sarcoma cells." (PMID 41169354, 2025). "We also found that miR-195 could directly bind to the mRNAs of SREBF1, FASN and ACACA in lung cancer cells resulting in decreases in lipid droplet formation induced by PM2.5 exposure." (PMID 36496421, 2022). "Also LKB1, which is decreased in human lung cancer as well as in the L-IkkαKA/KA SCC mouse model, may shuttle substrates into the elongation pathway by regulating ACACA." (PMID 26862848, 2016). "However, the level of total SREBP1 protein was not elevated obviously after PM2.5 exposure in either lung cancer cell lines based on western blot analysis, while its downstream proteins FASN and ACACA were clearly upregulated." (PMID 36496421, 2022).
glioma (6 papers, 2017 to 2025). A benign or malignant brain and spinal cord tumor that arises from glial cells (astrocytes, oligodendrocytes, ependymal cells). "Similarly, survival probability in hepatocellular carcinoma was reliably predicted by a glioma prediction model (ACSL3, ACSL6, ACACA, G6PD, SLC1A5, SLC7A11 and VDAC2) and by a risk model with a strong overlap with the genes in the glioma models (G6PD, HMOX1, LOX, SLC7A11, STMN1/Stathmin 1)." (PMID 34926298, 2021). "For the ACACA gene, an overexpression of 6 to 153-fold was found in CNS WHO grade 1 and 2 gliomas, while the expression levels of CNS WHO grade 3 and 4 gliomas showed 1534 to 5133-fold increases with respect to HMC3." (PMID 34573317, 2021). "Regarding the ACACA and ELOVL2 genes, we observed that these two genes were overexpressed in all glioma samples, and there was a relationship between the degree of tumor and expression." (PMID 34573317, 2021). "Given MiSL's prediction in AML and glioma and the positive validation of the IDH1mut-ACACA SL relationship in AML, it seems plausible that IDH1mut-ACACA SL relationship is valid in other IDH1 mutant tumours." (PMID 28561042, 2017). "Interestingly, in both colon adenocarcinoma (COAD) and lower-grade glioma (LGG) patients, patients with high ACACA expression demonstrated better OS, suggesting a potential context-dependent role for ACACA in different cancer types." (PMID 41169354, 2025). "Finally, the Krebs cycle and fatty acid synthesis pathways play central roles in cellular metabolism; we also found that the IDH1, SDHB, FASN, ACACA, and ELOV2 genes were overexpressed, resulting in significant disturbances in the cellular metabolism of gliomas." (PMID 34573317, 2021).
type 2 diabetes (5 papers, 2017 to 2023). "There also, down-regulation of the acetyl CoA metabolic network related genes (including ACACA) in obese individuals with type 2 diabetes compared to individuals with normal glucose tolerance has been demonstrated." (PMID 30787031, 2019). "A previous study reported that the acetyl CoA metabolic network related genes (including ACACA) was down-regulated in obese individuals with type 2 diabetes compared to those with normal glucose tolerance." (PMID 31235755, 2019).
non-small cell lung carcinoma (4 papers, 2023 to 2025). A group of at least three distinct histological types of lung cancer, including non-small cell squamous cell carcinoma, adenocarcinoma, and large cell carcinoma. "It has been considered to act as an oncogene, since inhibition of ACACA by siRNA or chemical inhibitors has been shown to decrease cell growth in prostate and non-small cell lung cancer." (PMID 36607556, 2023).
ovarian carcinoma (4 papers, 2018 to 2023). A malignant neoplasm originating from the surface ovarian epithelium. "Some scholars have constructed a prognostic grading model of ovarian cancer containing 5 ferroptosis-related factors (ALOX12, ACACA, SLC7A11, FTH1, and CD44) through biological analysis, which showed great value in the prognostic analysis of this disease." (PMID 37304234, 2023).
cervical cancer (3 papers, 2022 to 2023). A primary or metastatic malignant neoplasm involving the cervix. "Moreover, circ-ACACA may promote CC tumorigenesis and glycolysis by targeting the miR-582-5p/ERO1A signaling axis, indicating circ-ACACA can promote proliferation, invasion, migration, and glycolysis of cervical cancer cells." (PMID 35806027, 2022). "A previous research group established a 4-gene signature related to ferroptosis of cervical cancer patients (TFRC, ACACA, SQLE and PHKG2)." (PMID 36313765, 2022).
hyperlipidemia (3 papers, 2011 to 2024). "However, the activation of LXR promoted the transcription of liver lipid synthesis related genes like SREBF1, FASN, SCD, and ACACA, leading to liver steatosis and hyperlipidemia." (PMID 39645039, 2024). "Dysregulation of ANGPTL4 in podocytes under hyperlipidemia may be enacted through the AMPK/ACACA signalling pathway, which plays a crucial role in exercise-induced AMPK/ACACA activation in skeletal muscle." (PMID 38574398, 2024).
leukemia (3 papers, 2017 to 2024). A malignant (clonal) hematologic disorder, involving hematopoietic stem cells and characterized by the presence of primitive or atypical myeloid or lymphoid cells in the bone marrow and the blood. "We extensively validate a SL interaction identified by MiSL between the IDH1 mutation and ACACA in leukaemia using gene targeting and patient-derived xenografts." (PMID 28561042, 2017). "Here, the authors develop a computational algorithm that uses pan-cancer data to detect mutation-andcancer-specific SL partners and they validate a novel SL interaction between mutant IDH and loss of ACACA in leukaemia." (PMID 28561042, 2017). "The phosphoproteome screen indicated that the acetyl-CoA processing enzymes ACSS2 and ACACA might be metabolically supporting leukemia through stroma interactions." (PMID 38851813, 2024).
cholangiocarcinoma (2 papers, 2025). A carcinoma that arises from the intrahepatic biliary tree (intrahepatic cholangiocarcinoma) or from the junction, or adjacent to the junction, of the right and left hepatic ducts (hilar cholangiocarcinoma). "In cholangiocarcinoma, inhibiting ACACA enhances the acetylation of HSP90 so as to hinder the proliferation and migration of tumor cells." (PMID 41169354, 2025).
colon cancer (2 papers, 2021). "Further, among validated DEGs were those with established roles in colon cancer and CCSC (KLF6 and SQSTM1) and those with emerging roles (SPTLC2, SEC24D, and ACACA)." (PMID 34845203, 2021).
hypothyroidism (2 papers, 2024). Abnormally low levels of thyroid hormone. "In mice, mild hypothyroidism brought about by dietary iodine restriction, results in elevated hepatic expression of lipid utilization genes including ACACA, FASN, and CD36." (PMID 38658325, 2024).
melanoma (2 papers, 2019 to 2022). A malignant, usually aggressive tumor composed of atypical, neoplastic melanocytes. "Four DNFA enzymes – SCD, FASN, ACLY and ACSS2 – exhibit the highest levels of mRNA expression in skin cutaneous melanoma (SKCM) compared to other tumor types, whereas expression of ACACA is less elevated in melanomas." (PMID 31316083, 2019).
Sepsis (2 papers, 2021 to 2025). Sepsis is defined as life-threatening organ dysfunction caused by a dysregulated host response to infection. "Our PPI network analysis further unveils several key regulators like TOP2A, PAICS, HSPE1, HSP90AA1 and ACACA in the central hubs of dysregulated gene network in sepsis-induced ARDS." (PMID 33904373, 2021). "Consistently, PBMCs from sepsis patients exhibited increased mRNA expression of SREBF1, FASN, ACACA, and SCD1, supporting the clinical relevance of lipid biosynthesis activation." (PMID 40524162, 2025).
astrocytoma (1 paper, 2023). "These compounds induced SREBF1 but not SREBP1c-mediated lipogenic genes such as SCD1, ACACA and FASN in HepG2 cells or astrocytoma cells." (PMID 36674804, 2023).
cataract (1 paper, 2023). Partial or complete opacity of the crystalline lens of one or both eyes that decreases visual acuity and eventually results in blindness. "Although the ACACA gene has been ruled out as a causal gene for pediatric cataracts in a previous study, many studies have shown the metabolic relevance of this enzyme." (PMID 37511188, 2023).
colorectal tumors (1 paper, 2025). "A proteomic analysis performed by the same team of researchers revealed that the cancer-suppressing effect of CLDVs, particularly against colorectal tumors, was associated with the downregulation of Acetyl-CoA carboxylase 1 (ACACA)." (PMID 40648712, 2025).
developmental delay (1 paper, 2021). "We evaluated the possible disease-causing role of the ACACA gene in developmental delay and investigated the pathogenesis of ACC1 deficiency." (PMID 34552920, 2021).